AHCTF1 (AT-hook containing transcription factor 1)
Description:
Required for the assembly of a functional nuclear pore complex (NPC) on the surface of chromosomes as nuclei form at the end of mitosis. May initiate NPC assembly by binding to chromatin and recruiting the Nup107-160 subcomplex of the NPC. Also required for the localization of the Nup107-160 subcomplex of the NPC to the kinetochore during mitosis and for the completion of cytokinesis.
Synonyms: ELYS; TMBS62; MSTP108; MST108
Tractability: PROTAC: ubiquitination databases record sites on it; its protein half-life has been measured.
Gene: Protein-coding gene on chromosome 1 (246,839,098 to 246,932,063, reverse strand). Ensembl gene ENSG00000153207.
Subcellular location: Cytoplasm; Nucleus; Nucleus envelope; Nucleus matrix; Chromosome, centromere, kinetochore; Nucleus, nucleoplasm; Nucleus, nuclear pore complex
Subcellular location (Human Protein Atlas): Nuclear bodies; Nuclear membrane; Nucleoplasm
Pathways (Reactome):
Cell Cycle: Amplification of signal from unattached kinetochores via a MAD2 inhibitory signal; EML4 and NUDC in mitotic spindle formation; Mitotic Prometaphase; Postmitotic nuclear pore complex (NPC) reformation; Resolution of Sister Chromatid Cohesion; Separation of Sister Chromatids
Signal Transduction: RHO GTPases Activate Formins
Gene Ontology:
Biological process: nuclear pore complex assembly; regulation of cytokinesis; nucleocytoplasmic transport
Cellular component: chromatin; extracellular exosome; kinetochore; nuclear body; nuclear envelope; nuclear matrix; nuclear membrane; nuclear pore; nuclear pore outer ring; nucleoplasm; nucleus; cytosol; cytoplasm
Genetic constraint (gnomAD): Loss-of-function variants: 21 observed, 213.44 expected, observed/expected ratio (o/e) 0.0984, 90% interval 0.069 to 0.14. The upper end of that interval is the gene's LOEUF score, 0.14, which puts it in group 1 of 6, group 1 being the genes least tolerant of losing a copy. Missense variants: 2,058 observed, 2,425.8 expected, observed/expected ratio (o/e) 0.85, 90% interval 0.82 to 0.88. Synonymous variants: 729 observed, 853.46 expected, observed/expected ratio (o/e) 0.85, 90% interval 0.8 to 0.91.
Homologues: Orthologues: macaque AHCTF1 (95% identical), chimpanzee AHCTF1 (84% identical), pig AHCTF1 (81% identical), rabbit AHCTF1 (78% identical), guinea pig AHCTF1 (72% identical), dog AHCTF1 (71% identical), mouse Ahctf1 (71% identical), rat Ahctf1 (70% identical), tropical clawed frog ahctf1 (47% identical), zebrafish ahctf1 (42% identical), Drosophila melanogaster Elys (20% identical).
Diseases named in the same sentence as AHCTF1 in open-access papers:
AHCTF1 is named in the same sentence as 8 diseases in open-access papers, as found by Europe PMC text mining. Sharing a sentence is not in itself a finding about the gene and the disease. The quoted sentences say what the papers report.
colon cancer (3 papers, 2022). "For example, oncogenic MYC expression has been reported to be promoted by WNT signaling and AHCTF1 through SE-mediated gene gating and to increase the rate of colon cancer cell proliferation." (PMID 35186035, 2022).
hepatocellular carcinoma (2 papers, 2023 to 2024). A malignant tumor that arises from hepatocytes. "Gene expression analysis of patient samples from the liver hepatocellular carcinoma dataset in The Cancer Genome Atlas revealed a positive correlation between high expression of NUP107–160 complex components, including AHCTF1, and worse overall survival in HCC patients." (PMID 39000572, 2024).
ductal carcinomas (1 paper, 2007). "Majority of genes with this function were upregulated in ductal carcinomas such as AHCTF1, IRAK1, NRIP1, ADNP." (PMID 17389037, 2007).
melanoma (1 paper, 2023). A malignant, usually aggressive tumor composed of atypical, neoplastic melanocytes. "We next explored non‐coding mutations where we noted a recurrent hotspot mutation in the promoter of the AT‐hook containing transcription factor 1 (AHCTF1) (GRCh37 chr1: 247095271) affecting 2% of melanomas." (PMID 36219477, 2023).
tumor (3 papers, 2023). "Cell cycle proteins were evaluated based on their altered expression patterns (WAPAL, AHCTF1, etc.), phosphorylation patterns (CCNL1 T67, SMC4 S41, etc.), and inferred TF activities (SMARCA5, E2F3, etc.)in GC tumor tissues." (PMID 36788224, 2023).
AHCTF1 also shares sentences with these, for which no sentence is quoted: cancer (2 papers); HIV-1 infection (1); rectal cancer (1).